H6PD (hexose-6-phosphate dehydrogenase/glucose 1-dehydrogenase)
Description:
Bifunctional enzyme localized in the lumen of the endoplasmic reticulum that catalyzes the first two steps of the oxidative branch of the pentose phosphate pathway/shunt, an alternative to glycolysis and a major source of reducing power and metabolic intermediates for biosynthetic processes (By similarity). Has a hexose-6-phosphate dehydrogenase activity, with broad substrate specificity compared to glucose-6-phosphate 1-dehydrogenase/G6PD, and catalyzes the first step of the pentose phosphate pathway. In addition, acts as a 6-phosphogluconolactonase and catalyzes the second step of the pentose phosphate pathway (By similarity). May have a dehydrogenase activity for alternative substrates including glucosamine 6-phosphate and glucose 6-sulfate (By similarity). The main function of this enzyme is to provide reducing equivalents such as NADPH to maintain the adequate levels of reductive cofactors in the oxidizing environment of the endoplasmic reticulum. By producing NADPH that is needed by reductases of the lumen of the endoplasmic reticulum like corticosteroid 11-beta-dehydrogenase isozyme 1/HSD11B1, indirectly regulates their activity.
Synonyms: GDH; H6PDH; CORTRD1; G6PDH
Tractability: Antibody: UniProt predicts a signal peptide or a membrane-spanning region. PROTAC: ubiquitination databases record sites on it; its protein half-life has been measured.
Gene: Protein-coding gene on chromosome 1 (9,234,774 to 9,271,337, forward strand). Ensembl gene ENSG00000049239.
Subcellular location: Endoplasmic reticulum lumen
Subcellular location (Human Protein Atlas): Cytosol
Gene Ontology:
Molecular function: glucose-6-phosphate dehydrogenase activity; 6-phosphogluconolactonase activity; glucose 1-dehydrogenase (NAD+) activity; glucose 1-dehydrogenase (NADP+) activity; alcohol dehydrogenase (NAD+) activity; aldose 1-dehydrogenase activity; carbohydrate binding; carbonyl reductase (NADPH) activity; glucose 1-dehydrogenase [NAD(P)+] activity; NADP binding; oxidoreductase activity, acting on CH-OH group of donors
Biological process: pentose-phosphate shunt, oxidative branch; regulation of cortisol biosynthetic process; carbohydrate metabolic process; glucose metabolic process; NADP+ metabolic process; pentose-phosphate shunt; response to alcohol; response to nutrient levels
Cellular component: endoplasmic reticulum lumen; endoplasmic reticulum; sarcoplasmic reticulum
Genetic constraint (gnomAD): Loss-of-function variants: 49 observed, 61.47 expected, observed/expected ratio (o/e) 0.8, 90% interval 0.63 to 1.01. The upper end of that interval is the gene's LOEUF score, 1.01, which puts it in group 4 of 6, group 1 being the genes least tolerant of losing a copy. Missense variants: 1,085 observed, 1,096.2 expected, observed/expected ratio (o/e) 0.99, 90% interval 0.94 to 1.04. Synonymous variants: 480 observed, 478.14 expected, observed/expected ratio (o/e) 1, 90% interval 0.93 to 1.08.
Homologues: Orthologues: chimpanzee H6PD (99% identical), macaque H6PD (97% identical), guinea pig H6PD (86% identical), dog H6PD (85% identical), rabbit H6PD (85% identical), mouse H6pd (84% identical), pig H6PD (83% identical), rat H6pd (83% identical), tropical clawed frog h6pd (60% identical), zebrafish h6pd (53% identical), Drosophila melanogaster CG7140 (15% identical). Paralogues in human: G6PD (20% identical).
Diseases named in the same sentence as H6PD in open-access papers:
H6PD is named in the same sentence as 73 diseases in open-access papers, as found by Europe PMC text mining. Sharing a sentence is not in itself a finding about the gene and the disease. The quoted sentences say what the papers report.
breast carcinoma (14 papers, 2015 to 2025). "Both AGR2 and H6PD have been proposed to play a role in breast cancer progression, with elevated levels of these proteins being associated with increased breast cancer cell proliferation and migration." (PMID 40281598, 2025). "Given the restricted knowledge on 11β-HSD1-independent H6PD functions, we aimed to assess the H6PD interactome in breast cancer cells that are devoid of 11β-HSD1 expression." (PMID 40281598, 2025). "Due to the reported role of AGR2 in breast cancer and our observations of the impact of H6PD on breast cancer cell properties, we selected AGR2 from the pool of potential interactors for further investigations." (PMID 40281598, 2025). "Gene set enrichment analysis revealed multiple overlapping pathways enriched in breast cancer tissues with relatively high H6PD and AGR2 expression." (PMID 40281598, 2025). "Our earlier results showed that knockdown of H6PD in breast cancer cell lines reduces proliferation and/or migration." (PMID 40281598, 2025). "For example, H6PD was shown to impact the regulation of endoplasmic reticulum-stress, Ca2+-homeostasis and luminal redox balance in breast cancer cell lines as well as in skeletal muscles." (PMID 40281598, 2025). "For this purpose, gene set enrichment analysis was performed to identify enriched pathways in breast cancer tissue based on relatively high and low H6PD and AGR2 protein expression." (PMID 40281598, 2025). "Gene enrichment analysis was performed to investigate the pathway enrichment in breast cancer tissue in relation to H6PD and AGR2 protein expression." (PMID 40281598, 2025). "Glycolysis, fatty acid metabolism, hypoxia, angiogenesis, and epithelial to mesenchymal transition pathways were enriched in breast cancer tissue exhibiting relatively high H6PD and AGR2 expression." (PMID 40281598, 2025). "Downregulation of H6PD with short interfering RNAs in the murine colon and breast cancer cells correlated with reduced glucose uptake and decreased proliferation." (PMID 36009075, 2022). "Accumulating evidence indicates that H6PD plays an essential role in tumor initiation, progression, and drug resistance in multiple human cancers, including gallbladder, prostate, and breast cancer." (PMID 36009075, 2022). "Studies54,55 have also found that the downregulation of H6PD can affect the proliferation and migration of colon and breast cancer cells." (PMID 33723244, 2021). "Recent studies in human breast cancer cells have shown that the production of NADPH by hexose-6-phosphate dehydrogenase (H6PD) in the ER lumen is indispensable for the activity of SERCAs." (PMID 33282859, 2020). "In the present study, we demonstrated a pivotal role of H6PD in proliferation and migratory potential of 3 human breast cancer cell lines." (PMID 29295867, 2018). "In the current study, we showed that H6PD supports proliferation in 3 different breast cancer cell lines." (PMID 29295867, 2018). "Previous studies showed that loss of H6PD affects breast cancer cell properties, independent of 11β-HSD1." (PMID 40281598, 2025). "Knockdown of H6PD reduced the proliferation and migration of breast cancer cells." (PMID 36009075, 2022). "Thus, we identified a novel H6PD interactor, i.e. AGR2, started to explore breast cancer hallmark pathways to which this interaction might contribute to, and provided evidence that AGR2 enhances H6PD activity." (PMID 40281598, 2025). "These pathways have been shown to contribute to breast cancer progression, highlighting the importance of the potential AGR2 and H6PD interaction." (PMID 40281598, 2025). "These included, among others, pathways related to energy adaptation in breast cancer, such as fatty acid metabolism and glycolysis that were found to be enriched in breast cancer tissues, with elevated AGR2 or H6PD expression." (PMID 40281598, 2025).
breast carcinoma (continued). "First, the TCGA database was used to analyze H6PD and AGR2 mRNA expression correlation in breast cancer subtypes, and contribution of the two genes for survival of breast cancer patients." (PMID 40281598, 2025). "Three different breast cancer cell lines were analyzed for their AGR2 and H6PD protein expression levels by immunoblotting to identify a suitable cell line for Co-IP experiments." (PMID 40281598, 2025). "Therefore, we investigated whether high or low H6PD and AGR2 protein expression in breast cancer tissue correlates with the upregulation of pathways that are critical for breast cancer progression." (PMID 40281598, 2025). "We used the TNBC line MDA-MB-231 as a model system for the generation of a cell clone stably expressing H6PD-BirA*-HA because of our interest to start elucidating the role of H6PD and the luminal PPP in breast cancer cells and due to the absence of endogenous 11β-HSD1 expression in these cells." (PMID 40281598, 2025). "However, most breast cancer cell lines, including MDA-MB-231 and MCF7, do not express 11β-HSD1 and no other proteins directly interacting with H6PD have been described so far." (PMID 40281598, 2025).
Obesity (11 papers, 2015 to 2024). Accumulation of substantial excess body fat. "A previous genetic study reported that H6PD variants were associated with the PCOS phenotype by influencing obesity, insulin resistance and rarely responsible for hyperandrogenism." (PMID 26452272, 2015). "Many genes on this list are involved in different processes associated with T2DM development, such as obesity (SREBF1 and H6PD), inflammation (TGFB1), and insulin resistance (RPTOR and AKT1)." (PMID 39273245, 2024). "The R453Q and D151A variants of the H6PD gene are associated with polycystic ovarian syndrome (PCOS) and obesity, respectively." (PMID 33805313, 2021).
diabetes (9 papers, 2013 to 2026). "For diabetes, citrate synthase (CS) and malate dehydrogenase 1 (MDH1) impaired glucose oxidation via the TCA cycle, while hexose-6-phosphate dehydrogenase (H6PD) disrupted gluconeogenesis." (PMID 41531306, 2026).
glioma (4 papers, 2021 to 2024). A benign or malignant brain and spinal cord tumor that arises from glial cells (astrocytes, oligodendrocytes, ependymal cells). "Previous studies also indicated that upregulation of H6PD plays an essential role in purine metabolic reprogramming and glioma stem cell progression." (PMID 36009075, 2022). "By analyzing relevant genes in the TCGA and Chinese Glioma Genome Atlas, we found that the expression of G6PD and H6PD, the two genes encoding glucose-6 phosphate dehydrogenase, was increased in glioma patients, particularly H6PD." (PMID 33723244, 2021). "Furthermore, increased H6PD plays a crucial role in purine metabolic reprogramming and the progression of glioma stem cells." (PMID 36009075, 2022). "Low expression of H6PD was detected in the cerebral cortex, cerebellum, and low-grade glioma." (PMID 36009075, 2022). "Our findings indicate that targeting G6PD/H6PD, which are closely related to glioma patient survival, may serve as a promising therapeutic target for improved glioblastoma therapeutics." (PMID 33723244, 2021). "The gene expression levels of H6PD, G6PD, ADSL, APRT, GMPS, PRPS1, and IMPDH1 in human glioma patients were significantly higher than those in the control group." (PMID 33723244, 2021). "Taken together, upregulation of G6PD/H6PD in the PPP plays an important role in acidic-driven purine metabolic reprogramming and confers a predilection toward glioma progression." (PMID 33723244, 2021). "Key metabolic enzymes, such as H6PD or G6PD, may be potential targets for improving immune therapies and outcomes for glioma patients." (PMID 33723244, 2021). "Collectively, these results indicate that, under acidic conditions, G6PD and H6PD may play important roles in metabolic remodeling of GSCs but not differentiated glioma cells." (PMID 33723244, 2021).
Hyperglycemia (4 papers, 2013 to 2026). An increased concentration of glucose in the blood. "The present data indicate that fasting FDG uptake at least partially reflects H6PD activity and is thus enhanced under the redox stress induced by hyperglycemia despite the competition of serum concentration of unlabeled glucose." (PMID 31918925, 2020). "By contrast, the expected, direct, correlation between FDG uptake and H6PD catalytic function suggests that sustained hyperglycemia was followed by a divergent activation of reticular PPP in posterior and anterior brain areas." (PMID 33142766, 2020). "From the biochemical perspective, these findings indicate that the cell metabolic response to hyperglycemia-induced redox stress involves the activation of H6PD-triggered PPP and thus a selective modulation of the NAPDH/NADP ratio within the ER." (PMID 31918925, 2020). "Altogether, these data thus indicate that sustained moderate hyperglycemia eventually results in significant redox stress that is more severe in the posterior cortex due to the missing response of H6PD activity, suggesting an unexpected relevance of reticular PPP in brain antioxidant response." (PMID 33142766, 2020). "In agreement with this role, the H6PD enzymatic response to both STZ-DM and MTF matched the activation of the NADPH-dependent antioxidant responses to the increased generation of reactive oxygen species caused by chronic hyperglycemia." (PMID 31918925, 2020). "Finally, the evident response of H6PD, and the consequent activation of ER PPP, were coherent with the activation of NADPH-dependent antioxidant responses to the increase in ROS generation caused by chronic hyperglycemia." (PMID 31918925, 2020). "Similarly, the NADPH/NADP ratio was increased in the presence of hyperglycemia, while it was decreased by MTF treatment, nicely duplicating the response of SM in terms of H6PD function and avidity for FDG." (PMID 31918925, 2020).
glioblastoma (3 papers, 2021 to 2024). The most malignant astrocytic tumor (WHO grade IV). "The results showed that high expression of H6PD, ADSSL1, ADSS, and IMPDH1 was associated with worse prognosis for glioblastoma patients." (PMID 33723244, 2021). "In addition, we found that H6PD, but not G6PD, was associated with a poor survival rate for glioblastoma patients." (PMID 33723244, 2021).
Insulin resistance (3 papers, 2015 to 2024). Increased resistance towards insulin, that is, diminished effectiveness of insulin in reducing blood glucose levels. "Increasing WAT ER [NADPH]/[NADP+] in mice via hexose-6-phosphate dehydrogenase (H6PD) overexpression increased WAT NADPH-dependent 11β-hydroxysteroid dehydrogenase type 1 activity and cortiocosterone production, leading to slight weight gain, glucose intolerance, and insulin resistance." (PMID 39061889, 2024).
lung carcinoma (3 papers, 2019 to 2021). "Studying H6PD biological role in breast and lung cancer, here we show that gene silencing of this reticular enzyme decreases cell content of PPP intermediates and d-ribose, to a similar extent as G6PD silencing." (PMID 33335166, 2020). "Recently, it was reported that a paralog of G6PD, hexose-6-phosphate dehydrogenase (H6PD), that is present in the endoplasmic reticulum of cells, affects PPP flux in breast and lung cancer in a similar manner to G6PD." (PMID 33946927, 2021).
polycystic ovarian syndrome (3 papers, 2021 to 2024). "Hexose-6-phosphate dehydrogenase (H6PD) genes play the important role in polycystic ovarian syndrome (PCOS) by influencing various metabolic pathways and hormonal regulation." (PMID 39294254, 2024).
atherosclerosis (2 papers, 2011 to 2022). A disease characterized by the build-up of fatty material and calcium deposition in the arterial wall resulting in partial or complete occlusion of the arterial lumen. "Further experiments will therefore be required to identify the specific mechanism whereby H6PD Pro554Leu affects atherosclerosis susceptibility." (PMID 21858044, 2011). "Our results suggest a novel role for the H6PD gene in atherosclerosis susceptibility." (PMID 21858044, 2011). "In view of its regulatory role on 11β-HSD1 activity, the H6PD gene, which encodes the H6PDH protein, is a plausible candidate gene for atherosclerosis susceptibility." (PMID 21858044, 2011).
breast tumor (2 papers, 2018 to 2025). "Because both AGR2 and H6PD have been associated with breast tumor promoting effects, AGR2 was studied in more detail." (PMID 40281598, 2025).
retinoblastoma (2 papers, 2022 to 2023). A malignant tumor that originates in the nuclear layer of the retina. "Inhibition of H6PD expression levels produces suppressive effects on pancreatic cancer cells H6PD overexpression locally offset the effects of TUG1 deficiency on retinoblastoma proliferation and apoptosis." (PMID 37601754, 2023). "miR-516b-5p binding with taurine-upregulated gene 1 led to ectopic H6PD expression in retinoblastoma." (PMID 36009075, 2022).
Skeletal myopathy (2 papers, 2011 to 2020). "Other studies have shown that bioenergetics knockouts, such as H6PD null mice is responsible for inducing severe skeletal myopathy by altering sarcoplasmic reticulum redox state." (PMID 21909251, 2011). "Lack of H6PD results in a deteriorating skeletal myopathy, altered glucose homeostasis, ER stress and activation of the unfolded protein response." (PMID 32075690, 2020).
Catel-Manzke syndrome (1 paper, 2025). Catel-Manzke syndrome is a rare bone disease characterized by bilateral hyperphalangy and clinodactyly of the index finger typically in association with Pierre Robin sequence comprising micrognathia, cleft palate and glossoptosis. "This work reveals the molecular link between TGDS, UXS1, H6PD and Catel–Manzke syndrome." (PMID 40836090, 2025).
colon carcinoma (1 paper, 2021). "This placement and its tight correlation with FDG uptake were found to be strictly linked with the activity of the reticular enzyme hexose-6P-dehydrogenase(H6PD) in cell cultures of breast and colon carcinoma as well as in neurons and astrocytes." (PMID 34061902, 2021).
cortisone reductase deficiency (1 paper, 2020). A disorder in which there is a failure to regenerate the active glucocorticoid cortisol from cortisone via 11beta-HSD1. "The importance of the H6PD-11β-HSD1 interaction is clear in humans with ‘apparent’ cortisone reductase deficiency (ACRD) due to inactivating mutations in the H6pd gene." (PMID 32075690, 2020).
folate deficiency (1 paper, 2021). A nutritional condition produced by a deficiency of FOLIC ACID in the diet. "Several cancer types, including TNBC, have been shown to depend heavily on NADPH derived from H6PD, an enzyme in the PPP, to provide the reducing equivalents required for DHFR activity, with loss of H6PD resulting in folate deficiency." (PMID 34068120, 2021).
gastric cancer (1 paper, 2024). A primary or metastatic malignant neoplasm involving the stomach. "The hub proteins identified, CAT, PLEKHA4, HSP90AB1, TXN, EEF2, H6PD, and PDIA3, may play important roles in the treatment of gastric cancer using nintedanib." (PMID 38406279, 2024).
lymphoma (1 paper, 2023). A malignant (clonal) proliferation of B- lymphocytes or T- lymphocytes which involves the lymph nodes, bone marrow and/or extranodal sites. "On one side, HL PBMCs displayed an increased H6PD activity, suggesting an acceleration of glucose-6P flux through the ER-PPP, as opposed to the response of its G6PD-dependent cytosolic counterpart that was shared by both lymphoma types." (PMID 37444643, 2023).
Oligomenorrhea (1 paper, 2024). Infrequent menses (less than 6 per year or more than 35 days between cycles). "The network pharmacology analysis report found 988 PCOS-related genes, 108 hyperandrogenism-related genes, and 377 oligomenorrhea-related genes, and we finally shortlisted 5 common genes in PCOS, hyperandrogenism, and “oligomenorrhea”: NR3C1, PPARG, FOS, CYP17A1, and H6PD." (PMID 39294254, 2024).